CD44 (CD44 molecule (IN blood group))
Diseases named in the same sentence as CD44 in open-access papers (continued):
Sharing a sentence is not in itself a finding about the gene and the disease.
esophageal cancer (continued). "EGFR plays a key role in EMT induction in CD44+esophageal cancer cells though TGF-β." (PMID 28930282, 2017). "Interestingly, knockdown of ICAM-1 expression in esophageal cancer cell lines determines a concomitant upmodulation of CD44 expression; the same applies for CD44 in that CD44 downmodulation induces a concomitant ICAM-2 upmodulation." (PMID 28930282, 2017). "The percentage of CD44+/CD24− cells differed between the patients and showed differences between passages, indicating the presence of a potential esophageal cancer stem cell population, as seen in our EC cell lines." (PMID 35406578, 2022). "MIF serves as a non-cognate ligand for CXCR2 and CXCR4: MIF (and CXCR4) in the TME are adverse prognostic indicators in esophageal cancer, and it can induce CXCR ligand and regulators of macrophage infiltration like CD44." (PMID 26267609, 2015). "In Chen’s study of esophageal squamous cell carcinoma, up-regulated LINC-POU3F3 promoted the upregulation of tumor cell stem cell markers (CD133, CD44 and CD90), thereby enhancing the radiotherapy resistance of tumor cells and increasing the degree of malignancies of esophageal cancer." (PMID 35087800, 2021).
esophageal squamous cell carcinoma (25 papers, 2011 to 2025). Esophageal squamous cell carcinoma (ESCC) is a type of esophageal carcinoma (EC) that can affect any part of the esophagus, but is usually located in the upper or middle third. "High expression of CD44 is linked to enhanced malignant potential of esophageal squamous cell carcinoma, and Parkin-mediated mitophagy promotes CD44+ activity, while inhibition of mitophagy leads to oxidative stress and cell death." (PMID 38812059, 2024). "We previously showed that TDO2 expression was associated with CD44 expression in esophagus squamous cell carcinoma." (PMID 34101386, 2021). "Cells with high expression of CD44 (CD44H cells) are recognized as cancer stem cells involved in the development of esophageal squamous cell carcinoma (ESCC), which is characterized by high proliferation and drug resistance." (PMID 40968356, 2025). "One of the established clones (C44Mab−46; IgG1, kappa) reacted with CD44 standard isoform (CD44s)−overexpressed Chinese hamster ovary−K1 cells (CHO/CD44s) or esophageal squamous cell carcinoma (ESCC) cell lines (KYSE70 and KYSE770)." (PMID 35628345, 2022). "In this regard, mastermind-like 1 (MAML1), a molecule with few side effects, may be used for targeting CD44+ CSCs via repressing the canonical NOTCH pathway in esophageal squamous cell carcinoma (ESCC) patients." (PMID 35250573, 2022). "Additionally, ICAM1 and CD44 may have compensatory effects to maintain the dry characteristics of esophageal squamous cell carcinoma, indicating multiple targeted therapies that can be combined and considered in cancer treatment." (PMID 32195055, 2020). "CD44, TACSTD2, S100A14, and RHOD act as signatures to represent cancer‐spreading‐initiating cells in esophageal squamous cell carcinoma." (PMID 38864342, 2024). "While CD44 and CD133 have been recognized as stemness markers for esophageal squamous cell carcinoma cells." (PMID 37607071, 2023). "TDO2 expression correlated with CD44 and ALDH1 expression in BCs, which was consistent with our previous study on esophagus squamous cell carcinoma." (PMID 34101386, 2021). "In esophageal squamous cell carcinoma, IGFBP3 promotes tumor progression in a subset of tumor cells with a concurrent high expression of CD44." (PMID 29108245, 2017). "In esophageal squamous cell carcinoma cells in vitro, IGFBP-3 induces cells expressing high levels of CD44, a transmembrane glycoprotein involved in tumor growth and progression." (PMID 28778177, 2017). "For two esophageal SCC patients, samples representing the progression from normal to carcinoma in situ (CIS) and subsequently ESCC, we observed a gradual increase of CD44 expression." (PMID 22069487, 2011). "For esophageal SCC, we observed upregulation of CD44 in the absence of E-cadherin in 54% of the tumors (90 out of 166 tumors)." (PMID 22069487, 2011). "Similarly, the expression of B7-H4 correlated with stemness-related markers (i.e., CD44, SOX-2, SOX-9, OCT4) in NSCLC and esophageal squamous cell carcinoma (ESCC)." (PMID 41233805, 2025).
Sepsis (25 papers, 2012 to 2025). Sepsis is defined as life-threatening organ dysfunction caused by a dysregulated host response to infection. "Sepsis-induced emergency myelopoiesis was associated with significant reductions in the expression of several adhesion molecules (CD11b, CD44, and CD9) on myeloid cells." (PMID 41415274, 2025). "Plasma levels of soluble CD44 are significantly elevated in mice subjected to a sham operation or cecal ligation and puncture-induced sepsis, and the ectodomain of CD44 dose dependently increases endothelial barrier permeability in HUVEC monolayers." (PMID 40868017, 2025). "The results showed that, compared with the healthy control group, the expression of EXT1, HIF1A and HMMR was upregulated in sepsis, whereas the expression of CD44, EXT2 and SELL was downregulated in sepsis group." (PMID 40672940, 2025). "Here, we expand and complete these data by demonstrating that PD-L1+CD44+B220LowCD138+IgM+ regulatory PCs are induced in a murine model of sepsis and in critically ill septic patients." (PMID 40155394, 2025). "This open avenues for more research on the application of peptides to target other sepsis inflammatory-microenvironment’s overexpressed components such as selectins, CD44, TREM-1, and protease-activated receptor-1 (PAR-1)." (PMID 38637839, 2024). "Together, these studies will offer a more comprehensive understanding of CD44-ICD’s role in sepsis, highlighting its potential as a therapeutic target." (PMID 39201593, 2024). "Further study demonstrated that blocking CD44 decreased pulmonary neutrophilia and also attenuated sepsis-induced lung edema and tissue injury." (PMID 35205254, 2022). "Various studies demonstrated CD44’s role in the extravasation and recruitment of lymphocytes to the lungs, kidneys, and joints in inflammatory diseases, including sepsis, chronic kidney disease, cardiac fibroblast, and SLE." (PMID 35205254, 2022). "Only three genes (EGR1, MMP8, and cd44) were shown to be prevalent in the DEGs of sepsis, SLE, and CRS." (PMID 35205254, 2022). "A prominent role for CD44–HA interactions in immune cell recruitment to the liver was first observed in a model of acute hepatic inflammation due to sepsis/endotoxemia." (PMID 25741341, 2015). "In another murine model of polymicrobial sepsis, CD44 was shown to mediate pulmonary recruitment of neutrophils and the use of antibodies targeting CD44 inhibited lung damage." (PMID 24376813, 2013). "In a similar way, it has been shown that HA exhibits a CD44-dependent protection against LPS-induced murine sepsis by binding to TLR4 and blocking excessive inflammatory cytokine production." (PMID 22721434, 2012). "In a murine model of sepsis that recapitulates immune alterations observed in patients, here we demonstrate that PD-L1+CD44+B220LowCD138+IgM+ regulatory plasma cells are induced in spleen and regulate ex vivo proliferation and IFNɣ secretion induced by stimulation of T splenocytes." (PMID 40155394, 2025). "Plasma levels of soluble CD44 are significantly elevated in mice subjected to a sham operation or cecal ligation and puncture-induced sepsis; the ectodomain of CD44 dose-dependently increases the endothelial barrier permeability in human umbilical vein endothelial cell (HUVEC) monolayers." (PMID 40868017, 2025). "Thus, besides autoimmune diseases, the current results expand the immunoregulatory role of CD138+CD44+HLA-DRhigh PCs as IL-10 producers and regulators of T-cell proliferation after sepsis as well." (PMID 40155394, 2025). "Additionally, comparative studies between the LPS and CLP models in these knockout mice will help confirm the consistency of CD44-ICD’s role across different sepsis models." (PMID 39201593, 2024). "This present study may be the first report to discover that CD44-ICD plays a crucial role in the sepsis-relative inflammatory response." (PMID 39201593, 2024).
Sepsis (continued). "Moreover, investigating TLR4 and other regulatory pathways will provide insights into how CD44-ICD interacts with broader molecular networks during sepsis." (PMID 39201593, 2024). "CD44 mediates polymicrobial sepsis‐induced pulmonary recruitment of neutrophils." (PMID 36336784, 2022). "This increase in CD44 expression could occur either be through homeostatic proliferation following the severe lymphodepletion that occurs following a septic event or potentially through antigen release due to sepsis-induced tissue damage." (PMID 33191915, 2020). "The results indicated that ITGAM, CD44, C3AR1, and IL2RG exhibited significantly higher expression in the sepsis group compared to the SIRS group." (PMID 38678059, 2024). "Five characteristic genes—BCL2A1, CD44, ADGRG1, TGIF1, and ING3—were identified, which enabled the prediction of mortality of sepsis." (PMID 37069215, 2023). "Based on degree centrality, 27 hub genes were selected, in which six genes (MMP9, CD44, EGR1, ACTN2, TNNT3, and PTGS2) were selected on the basis of a multi-network variable selection approach and validated in a well-established sepsis mice model." (PMID 35205254, 2022). "We examined the long-term consequences of sepsis on CD4+ and CD8+ naive (CD62Lhi CD44-) and effector/memory (CD44+CD62Llo or +) T lymphocytes." (PMID 30730978, 2019). "Nevertheless, while acting as a receptor, Neutrophils connected with plasma cells by up-regulating MIF-(CD74+CD44) (strong) in both sepsis and control group, but connected with CD8+ T cell, NK cell, B cell, and DC by down-regulating MIF-(CD74+CD44) in both sepsis and control group." (PMID 39108261, 2024). "Furthermore, a meta-analysis identified four genes, namely ITGAM, CD44, C3AR1, and IL2RG, which were highly expressed in the sepsis group compared to the normal group (P < 0.05)." (PMID 38678059, 2024). "The boxplot revealed 26 differentially expressed genes between the sepsis-induced ALI and control samples: Ncf2, Slc2a6, Cd44, Txnip, Slc2a1, Ubc, Hspb1, Zfp36, Arntl, Ddit4, Tnfaip3, Txnrd1, Mt1, Hmox1, Gch1, Gclc, Stat3, Egfr, Hif1a, Bach1, Socs1, Dusp1, Cdkn1a, Fth1, Steap3, and Alox12." (PMID 37081490, 2023). "In a model of septicemia, when bacteria were in the bloodstream, staphylococci significantly inhibited the interaction between P- and E-selectins on the endothelial cell membrane and PSGL-1, ESL-1, CD15, and CD44, expressed on the membrane of neutrophils." (PMID 36144298, 2022). "However, only three genes (CD44, MMP9, and EGR1) were found to be significantly upregulated in the sepsis model, correlating with our bioinformatic results." (PMID 35205254, 2022). "For example, neutrophil recruitment to the liverhas been studied in lipopolysaccharide (LPS) induced sepsis model.In this model, CD44, not Mac-1 was considered to be responsible for neutrophilrecruitment." (PMID 29977977, 2018). "As expected, chronic T. gondii infection maintained a pool of CD4+ and CD8+ T cells (CD4+CD44+ and CD8+CD44+ T cells, respectively) independent of sepsis, thus confirming that such cells were activated by T. gondii." (PMID 28439500, 2017). "The role of CD44-ICD on hepatic inflammation during sepsis has never been investigated." (PMID 39201593, 2024). "Interestingly, we did not observe any increase in the frequency of CD44 on CD8+ T cells due to ethanol alone or following sepsis." (PMID 27861506, 2016). "Therefore, overexpressed CD44 in SLE, sepsis, and CRS could serve as a disease biomarker." (PMID 35205254, 2022).
colitis (24 papers, 2014 to 2025). Inflammation of the colon. "Colitis induced by DNBS administration caused a marked presence of CD44 positive cells when compared to the control group." (PMID 33092298, 2020). "Specifically, in TNBS-induced colitis, Cd44, Numa1, S100a8, S100a9, Timp1 and Xbp1 were more highly expressed, while Cidec and Rag1 were less expressed." (PMID 38778086, 2024). "Consistent with previous work, in the DSS mouse model, the expression levels of Cd44, S100a8, S100a9 and Timp1 were greater in the mice with colitis; while the expression level of Ndrg1 was lower in the mice with colitis." (PMID 38778086, 2024). "This is emphasized by a significant lower abundance (p = 0.001592) of total amount of VSOPs containing F4/80+, CD68+ macrophages, expressing CD44 in transfer colitis." (PMID 35903065, 2022). "In DSS-induced colitis, VSOPs seem to be taken up by CD44 expressing macrophages in the periphery, which then get recruited to the inflamed colon by binding to the endothelial cells expressing high amounts of HA." (PMID 35903065, 2022). "We found that the amounts of CD8+ and CD8+CD44+ IFN-γ+ T-cells increased markedly in colonic LP of IL-21RKO mice with DSS-induced colitis." (PMID 27545302, 2016). "Furthermore, the IMC data displayed a lower amount of CD44-expressing macrophages in the colon of transfer colitis mice." (PMID 35903065, 2022). "The levels of effector memory T cells, such as CD4+CD62L− (CD4+TEM) T cells, and the expression of the homing cell adhesion molecule CD44 in the peripheral blood, spleen, lamina propria of the small intestine, and mesenteric lymph nodes of mice with colitis were found to be decreased." (PMID 33597887, 2020). "CD4+ Tm (CD4+ CD45RBhigh) cells isolated from the lamina propria of mice with colitis were cultured in vitro for 8 weeks and transplanted into SCID mice to cause acute colitis, and CD4+CD44+CD62L− memory T cells were found to overaggregate in the lamina propria of the colon." (PMID 33597887, 2020). "In conclusion, iPSC-MSCs promoted epithelial cell proliferation to accelerate mucosal healing in a murine colitis model via TSG-6 through hyaluronan–CD44 interactions in an Akt-dependent manner, demonstrating a patient-specific “off-the-shelf” format for IBD treatment." (PMID 31558705, 2019). "In the current study, we found that TSG-6 released by iPSC-MSCs plays an essential role in determining the therapeutic effects of iPSC-MSCs on murine colitis by stimulating intestinal epithelial proliferation through interactions between CD44 and hyaluronic acid (HA)." (PMID 31558705, 2019). "HiPSCs-MSCs could promote epithelial cell proliferation for mucosal healing in a murine colitis model via the interactions of TSG-6 and hyaluronan-CD44 in an Akt-dependent manner." (PMID 38720903, 2024). "However, in DSS-induced colitis VSOPs further strongly co-localized with CD68, F4/80 double positive macrophages expressing CD44." (PMID 35903065, 2022). "The findings demonstrate that (i) Ab-mediated IL-10 neutralization leads to progressive colitis with a reduction in Foxp3+ regulatory T cells and increased numbers of CD8+CD44+ memory T cells as well as activated CD4+CD69+ and CD8+CD69+ T cells in uninfected mice." (PMID 27611574, 2016). "Indeed, similar to the literature, we could measure the reduced expression of the activation marker CD44 in the spleens of ONX 0914 treated mice, already at early stages of colitis." (PMID 40422192, 2025). "Furthermore, various transmembrane receptors such as CD44, folate (FA), mannose receptors and CD98, are overexpressed not only on the inflamed colitis tissue but also on activated macrophage surfaces, providing potential binding sites for active-targeting systems." (PMID 36297553, 2022).
colitis (continued). "As CD44-expressing macrophages are not as prominent in the colon of transfer colitis mice and the amount of hyaluronic acid in their colon tissue is not changing during the course of inflammation, suggests CD44+ macrophages and HA as the main structures for VSOP binding and accumulation." (PMID 35903065, 2022). "Thus, we examined the expression of memory markers (CD44 and Eomes), NK cell receptors (NKG2D and Ly49a), cytolytic molecules (FasL and Perforin), and pro-inflammatory cytokines (IFNγ and TNFα) in MLN-derived NK1.1+CD8+ T cells from Yeti/CD1d KO mice during DSS-induced colitis." (PMID 30333822, 2018).
diabetes (24 papers, 2013 to 2026). "CD44 expression is associated with altered immune function in mice and has been reported to affect atherosclerosis and diabetes." (PMID 35410390, 2022). "This method of targeting CD44 has been used in murine models of collagen-induced arthritis and diabetes, and both showed improvement in disease pathogenesis." (PMID 39411720, 2024). "After adjustment of age, sex, BMI, history of diabetes mellitus, hypertension, hyperlipidemia, smoking, LDL-C, HDL-C, triglyceride, eGFR, hs-CRP, and CD44, HA levels were independently associated with plaque types." (PMID 33644134, 2021). "CD44 is an important mediator in inflammation and anti-CD44 antibody successfully delays the onset of diabetes in the NOD mouse." (PMID 29594371, 2018). "Recent reports regarding anti-CD44 therapies mostly cover either inflammatory diseases and diabetes, or rather concentrate on the clinical aspects of oncological treatments." (PMID 27463372, 2016). "In this study, both CD44 standard and CD44v3–v10 cDNAs induced resistance to diabetes to the same extent, and the resistance was antibody mediated." (PMID 25954275, 2015). "Diabetes upregulated Hyal-1, CD44, RHAMM and reactive oxygen species in rat retinas." (PMID 41789111, 2026). "Nanoflowers demonstrate rapid wound healing due to reduced inflammation, tissue regeneration, and angiogenesis in the diabetes-induced wound model by modulating tumor necrosis factor-α, CD-44, Ki-67, collagen deposition, ROS, interleukin-1β (IL-1β), IL-8, and IL-6 expression." (PMID 41737838, 2026). "When scrutinizing CD44 status in erythroblasts, the individual afflicted with diabetes (sample Nr." (PMID 36100762, 2023). "CD44 has a destructive effect on diabetes, and knocking down its expression may help control the disease, reduce the likelihood of diabetic foot, and even reduce other diabetic complications, such as diabetic retinopathy and diabetic nephropathy." (PMID 37904700, 2023). "Based on the results of previous research, it was quite possible that the increased circulating levels of GPNMB caused abnormal phosphorylation of AKT via binding to CD44 and then stimulated anomalous activation of AKT/PI3K signaling to promote lipogenesis and provoke diabetes." (PMID 36875463, 2023). "The approach of narrowing down potential genes of interest using publicly available datasets and subsequently confirming the hypotheses in the laboratory has led to discoveries such as the role of CD44 in diabetes." (PMID 36289702, 2022). "We hypothesized that the relationship between CD44’s and diabetes may only be evident in an obese state or perhaps in genetically susceptible individuals." (PMID 35410390, 2022). "Furthermore, daily injection of the anti-CD44 antibody decreased blood glucose levels, weight gain, liver steatosis, and insulin resistance to the levels lower than anti-diabetes drugs metformin and pioglitazone." (PMID 25954275, 2015). "Up till now, no direct evidence has linked HABP2 with diabetes; however, its ligand, hyaluronan, has been suggested to interact with CD44 and PKC and reduce inflammation in diabetic nephropathy mice." (PMID 23671866, 2013). "Thus, CD44 remains one of many factors that contribute to the metabolic consequences of calorically rich diets, and additional genetic factors contribute to the development of diabetes and fatty liver disease." (PMID 35410390, 2022). "Drugs closely related to diabetes, such as Fenretinide, Dimethylamine parthenolide, Chelerythrine, etc., have obvious positive correlation with LCP2, TYROBP, RPL3, CDK4, and CD44." (PMID 36755923, 2023). "First, we selected the central core sites in the PPI network of AS, DN, DR and found six characteristic genes of diabetes (TYROBP, LCP2, CCL2, CD44, RPL3, CDK4)." (PMID 36755923, 2023). "This CD44 signature effectively distinguishes between DKD and diabetes." (PMID 39050866, 2024).